BCR (BCR activator of RhoGEF and GTPase)
Diseases named in the same sentence as BCR in open-access papers (continued):
Sharing a sentence is not in itself a finding about the gene and the disease.
chronic myeloid leukemia (continued). "One of the classical examples is the oncogenic BCR-ABL tyrosine kinase fusion, the product of the Philadelphia chromosome, which results from a recurrent translocation between chromosomes 9 and 22 and constitutes the hallmark of chronic myelogenous leukemia (CML)." (PMID 29455671, 2018). "Importantly, the association between miR-130a expression and fusion proteins was first proposed by Suresh and collaborators who confirmed that miR-130a was downregulated in a BCR-ABL-dependent manner in chronic myelogenous leukemia (CML) when compared with normal controls." (PMID 29493383, 2018). "Thus, Fli-1 transactivating compounds may cooperate with Imatinib for the treatment of chronic myelogenous leukemia (CML) driven by BCR-ABL." (PMID 28052010, 2017). "The Philadelphia chromosome is a translocation between the ABL1 gene on chromosome 9 and the BCR gene on chromosome 22, leading to the formation of a constitutively active hybrid tyrosine kinase that contributes to the development of leukemia, especially chronic myelogenous leukemia (CML)." (PMID 28257090, 2017). "Chronic Myeloid Leukemia (CML) could be considered as the paradigm for non-genomic loss of function of tumor suppressors due to the ability of BCR-ABL to directly promote functionally inactivation of several tumor suppressors." (PMID 27184141, 2016). "Chronic myeloid leukemia (CML) is a clonal myeloproliferative disorder of a pluripotent hematopoietic stem cell (HSC) and the first human cancer that was found associated with a single consistent and causative molecular alteration, the oncogenic fusion tyrosine kinase BCR-ABL." (PMID 27048866, 2016). "One such cancer, chronic myelogenous leukemia (CML), is associated with a characteristic translocation between chromosomes 9 and 22, called the “Philadelphia chromosome (Ph),” which encodes a fusion protein composed of breakpoint cluster region (BCR) protein and the PTK Abl1, called BCR-ABL." (PMID 25822986, 2015). "These potentially include patients with fusions of JAK2 with PCM1, ETV6 and BCR, T-cell large granular lymphocytic leukaemia, chronic lympho-proliferative disorders of natural killer cells, Waldenstrom’s Macroglobulinaemia, chronic myeloid leukaemia and chronic lymphocytic leukaemia." (PMID 26131691, 2015). "The BCR-ABL translocation is found in chronic myeloid leukemia (CML) and in Ph+ acute lymphoblastic leukemia (ALL) patients." (PMID 25029499, 2014). "The first oncogene discovered as the direct etiological basis of a malignancy, the BCR/ABL1 translocation in chronic myeloid leukemia (CML), results in dysregulated tyrosinase activity, which can be treated using the tyrosine kinase inhibitor Imatinib." (PMID 24499728, 2014). "Dasatinib (BMS-354825) is an FDA-approved small molecular compound that was developed primarily to treat chronic myeloid leukemia (CML) as a multi-targeted tyrosine kinase inhibitor against wild-type BCR-ABL and SRC family kinases." (PMID 24918603, 2014). "Expression of the Philadelphia chromosome (Ph), resulting from fusion of the non-receptor tyrosine kinase ABL1 on chromosome 9 with BCR on chromosome 21, is the hallmark of chronic myeloid leukemia (CML), but is also found in 20-30% of acute lymphoblastic leukemia (ALL) cases." (PMID 21299849, 2011). "For instance, chronic myeloid leukemia (CML) is characterized by the expression of a chimeric BCR-ABL oncoprotein in hematopoietic precursor cells which behaves as a potent inhibitor of apoptosis." (PMID 19430526, 2009). "Imatinib mesylate induces complete cytogenetic responses in patients with chronic myeloid leukemia (CML), yet many patients have detectable BCR-ABL transcripts in peripheral blood even after prolonged therapy." (PMID 19749982, 2009).
chronic myeloid leukemia (continued). "Chronic myelogenous leukaemia was the first human cancer to be associated with a consistent chromosomal abnormality, the Philadelphia chromosome, a translocation that juxtaposes the 3′ sequence from the ABL1 proto-oncogene on chromosome 9 with the 5′ sequence from the BCR gene on chromosome 22." (PMID 18665178, 2008). "Asciminib, a first-in-class allosteric BCR::ABL1 (STAMP) inhibitor, has demonstrated efficacy and favorable tolerability in chronic myeloid leukemia, but its optimal role in Ph+ ALL remains to be defined." (PMID 42042193, 2026). "Chronic Myeloid Leukemia (CML) is primarily driven by the Philadelphia chromosome, producing the BCR::ABL1 fusion protein." (PMID 41225551, 2025). "In chronic myeloid leukemia (CML), the BCR–ABL fusion protein is a classical target for TKI therapy with imatinib." (PMID 41247642, 2025). "In chronic myeloid leukemia (CML), less than 2% of cases express atypical or rare BCR::ABL1 transcripts." (PMID 41211450, 2025). "DLI is used to amplify the graft versus leukemia (GvL) effect and has shown particular success in cases of chronic myeloid leukemia (CML) when addressing impending relapse, especially when detected at the cytogenetic (BCR-ABL) or molecular level." (PMID 40574863, 2025). "The BCR::ABL1 fusion gene is the primary molecular marker of chronic myeloid leukemia (CML)." (PMID 40166069, 2025). "Chronic myeloid leukemia (CML) is a stem cell-derived hematological malignancy with genomic aberrations appearing in hematopoietic stem and progenitor cells characterized by a fusion oncogene BCR/ABL." (PMID 40346054, 2025). "Examples include BCR::ABL1 in LAMA84, a blast phase chronic myeloid leukaemia (CML-BP) cell line and EML4::ALK in NCI-H2228 (also known as H2228), a lung adenocarcinoma cell line." (PMID 41421967, 2025). "Chronic Myeloid Leukaemia (CML) is a haematologic malignancy characterised by the formation of the Philadelphia chromosome, harbouring the BCR::ABL1 fusion gene." (PMID 41008876, 2025). "In chronic myeloid leukemia (CML), GA reverses resistance to imatinib and doxorubicin by inhibiting BCR-ABL and its downstream STAT5, ERK1/2, and Akt signaling pathways, while reducing pregnane X receptor (PXR) expression." (PMID 41311720, 2025). "In chronic myeloid leukemia (CML), hypermethylation of miR-203 has been shown to confer a growth advantage to tumor cells by downregulating the oncogenic BCR-ABL fusion protein." (PMID 40699626, 2025). "In addition to qPCR for monitoring BCR::ABL1, ABL1 kinase domain point mutation analysis provides important clinical information in predicting resistance and choosing appropriate tyrosine kinase inhibitor (TKI)/treatment strategies in chronic myeloid leukaemia (CML)." (PMID 39403025, 2025). "Chronic myeloid leukemia (CML) is classified into three subtypes based on the BCR breakpoint, the rarest of which is micro BCR::ABL1 (also known as e19a2 BCR::ABL1), which encodes a P230 fusion protein." (PMID 40452681, 2025). "Main pathways of tyrosine kinase inhibitor (TKI) resistance in chronic myeloid leukemia (CML), distinguishing between BCR::ABL1-dependent and independent mechanisms." (PMID 40823259, 2025). "FISH results show BCR/ABL positivity in neutrophils, indicating transformation of the patient to chronic myeloid leukemia." (PMID 41341402, 2025). "The BCR-ABL transcript is part of the tyrosine kinase class of enzymes, being related to the development of Chronic Myeloid Leukemia (CML) and some forms of severe Acute Lymphoblastic Leukemia (ALL)." (PMID 41157162, 2025). "Chronic myeloid leukemia (CML) is a clonal myeloproliferative neoplasia characterized by the BCR::ABL1 fusion gene, which codifies the BCR-ABL protein with increased tyrosine kinase activity." (PMID 40565143, 2025).
chronic myeloid leukemia (continued). "In contrast, chronic myeloid leukemia (CML) progresses more slowly and is marked by the presence of the Philadelphia chromosome (BCR-ABL fusion gene), which promotes the uncontrolled proliferation of myeloid cells." (PMID 40723215, 2025). "Chronic Myeloid Leukemia (CML) is a myeloproliferative disorder characterized by the presence of the Philadelphia chromosome, which produces the BCR::ABL1 fusion protein." (PMID 41225551, 2025). "Imatinib is a tyrosine kinase inhibitor that targets the BCR-ABL fusion protein, which is present in chronic myeloid leukemia/CML cells." (PMID 39817564, 2025). "Tyrosine kinase inhibitors (TKIs) inhibit the disease-defining BCR::ABL1 fusion kinase, are highly effective for chronic myeloid leukemia (CML), and have revolutionized its treatment." (PMID 38776875, 2024). "Stachydrine effectively inhibits several receptor tyrosine kinases, including BCR-ABL, which is crucial in the treatment of chronic myeloid leukemia (CML)." (PMID 39170783, 2024). "The most crucial path passes through the phenotype Ph+ ALL, the disease chronic myelogenous leukemia, BCR-ABL1 positive, and the gene BCR, before connecting to Bosutinib via the drug protein relation (right)." (PMID 39372928, 2024). "Chronic myeloid leukemia (CML) comprises ~15 to 20% of all adult leukemias and the development of oral BCR::ABL1-targeted tyrosine kinase inhibitors (TKIs) has revolutionized management." (PMID 38879611, 2024). "For example, chronic myeloid leukemia (CML) mainly results from the translocation between the long arms of chromosomes 9 and 22 leading to the BCR-ABL fusion (Philadelphia chromosome)." (PMID 39512772, 2024). "For example, dasatinib (DB01254) is an oral dual BCR/ABL and SRC family tyrosine kinase inhibitor approved for use in patients with chronic myelogenous leukemia (DrugBank: dasatinib)." (PMID 38791306, 2024). "Chronic myeloid leukaemia (CML) is a haematological malignancy characterised by a reciprocal translocation between chromosome 9 and 22 to give rise to the oncogene BCR::ABL19,10." (PMID 38316788, 2024). "In chronic myeloid leukemia (CML) and a large fraction of B-cell acute lymphoblastic leukemias, the constitutive tyrosine kinase activity of BCR::ABL1 is the central driver of leukemogenesis." (PMID 39715735, 2024). "Since the development of the first‐generation Tyrosine Kinase Inhibitor (TKI), it has played a crucial role in the treatment of BCR::ABL1‐positive acute lymphoblastic leukemia (ALL) and chronic myeloid leukemia (CML)." (PMID 39440695, 2024). "The BCR::ABL1 oncogene results from the translocation of chromosome 9 and chromosome 22, also termed the “Philadelphia chromosome”, found in patients with chronic myeloid leukemia (CML)." (PMID 38424137, 2024). "Chronic myeloid leukemia (CML), characterized by the presence of the BCR::ABL1 fusion gene, has undergone a transformative shift with the introduction of tyrosine kinase inhibitors (TKIs)." (PMID 39252937, 2024). "The BCR-ABL fusion protein drives the malignant proliferation of myeloid stem cells and has been shown to be a major pathogenetic mechanism in chronic myelogenous leukemia (CML)." (PMID 39272847, 2024). "In patients with chronic myeloid leukemia (CML), SHIP1 had been shown to be phosphorylated by BCR-ABL and subsequently degraded." (PMID 38992657, 2024). "Chronic myeloid leukemia (CML) is characterized by the accumulation of myeloid precursors and mature myeloid cells and is driven by translocations between the BCR serine/threonine kinase gene and the ABL tyrosine kinase, resulting in a constitutively active ABL tyrosine kinase." (PMID 38234720, 2023). "In Chronic Myeloid Leukemia (CML), the use of the 1st generation TKI imatinib to target the cancer driver, BCR::ABL1, results in 10 year survival rates of over 83%, approaching that of the healthy age-matched population." (PMID 37567965, 2023).
chronic myeloid leukemia (continued). "Chronic myeloid leukemia (CML) is characterized by a reciprocal translocation between chromosomes 9 and 22 that produces a gene fusion product on chromosome 22 between BCR and ABL." (PMID 36991452, 2023). "In opposition to its pro-survival role, autophagy is also involved in the degradation of the fusion proteins PML-RARA and BCR-ABL which contribute to antileukemic responses in acute promyelocytic leukemia (APL) and chronic myeloid leukemia (CML), respectively." (PMID 37296673, 2023). "The formation of the BCR-ABL fusion gene drives human chronic myeloid leukemia (CML)." (PMID 38103082, 2023). "Chronic myeloid leukemia (CML) is characterized by a chromosomal translocation leading to the generation of the Philadelphia (Ph) chromosome and expression of the BCR::ABL1 fusion protein." (PMID 37553873, 2023). "Chronic myeloid leukemia (CML) is effectively treated with tyrosine kinase inhibitors (TKIs), targeting the BCR::ABL1 oncoprotein." (PMID 38012567, 2023). "BCR::ABL1 fusion has significant prognostic value and is screened for chronic myeloid leukemia (CML) disease monitoring as a part of routine molecular testing." (PMID 37248544, 2023). "In chronic myeloid leukemia, CRKL is a crucial BCR/ABL substrate that can bind to both c-ABL and BCR/ABL." (PMID 37894400, 2023). "The prognosis of chronic myeloid leukemia (CML) on tyrosine kinase inhibitor (TKI) treatment is based on the quantification of BCR::ABL1 fusion gene transcript copy number, harmonized by an international scale (IS) based on TaqMan-based real-time quantitative PCR (qRT-PCR)." (PMID 37212909, 2023). "In 2001, Gleevec, the first small molecule BCR–ABL TKI, was introduced to the market as a treatment for chronic myelogenous leukemia (CML)." (PMID 38077251, 2023). "Withaferin A binding potential and interaction to the catalytic site of BCR-ABL, an oncogenic protein promoting cell proliferation and inhibition of apoptosis in chronic myeloid leukemia (CML), was determined as a result of computational analysis." (PMID 36339589, 2022). "Chronic myeloid leukemia (CML) has as its main characteristic the reciprocal and balanced translocation of chromosomes 9 and 22 t (9q34 and 22q11), which results in the Philadelphia chromosome and fusion of the BCR-ABL genes." (PMID 35205374, 2022). "In chronic myeloid leukaemia (CML), tyrosine phosphorylation of β-catenin on residues Y86 and Y654 by the oncogenic fusion protein BCR-ABL led to its reduced affinity for the DC, and subsequent increase and activity in the nucleus." (PMID 35352805, 2022). "A hematopoietic stem cell condition called Chronic Myeloid Leukemia (CML) results from a translocation of chromosomes 9 and 22′s long arms, which contains the BCR-ABL fusion oncogene." (PMID 36547200, 2022). "Results showed that DMP11 at a dose of 5 nM significantly degraded the BCR-ABL fusion protein of wild-type and imatinib-resistant chronic myeloid leukemia cell lines and found that the SRC protein (Yes/Fyn/Fgr) also showed a dose-dependent degradative effect." (PMID 36349200, 2022). "Chronic myeloid leukemia (CML) is a bone marrow proliferative hematopoietic cell malignancy characterized by the BCR::ABL1 fusion gene that is formed by genetic translocation between chromosome 9 and chromosome 22." (PMID 36263131, 2022). "Ponatinib, the only third‐generation pan‐BCR::ABL1 inhibitor with activity against all known BCR::ABL1 mutations including T315I, has demonstrated deep and durable responses in patients with chronic‐phase chronic myeloid leukemia (CP‐CML) resistant to prior second‐generation (2G) TKI treatment." (PMID 36054756, 2022). "We analyzed BCR::ABL1 expression at stop and in the first month after discontinuation in 168 chronic myeloid leukemia patients who stopped imatinib or 2nd generation tyrosine kinase inhibitors (2G-TKIs) while in sustained deep molecular response." (PMID 36208021, 2022).
chronic myeloid leukemia (continued). "For example, breakpoint cluster region-Abelson (BCR-ABL) tyrosine kinase and EGFR are overexpressed in imatinib-resistant chronic myeloid leukemia (CML) and crizotinib-resistant anaplastic lymphoma kinase (ALK)-positive NSCLC, respectively." (PMID 36140200, 2022). "The inclusion of BCR::ABL1 tyrosine-kinase inhibitor (TKI) in the first-line treatment of chronic myeloid leukemia (CML) and positive B-cell precursor acute lymphoblastic leukemia (ALL) with Philadelphia (Ph) chromosome increased the life expectancy of these patients." (PMID 35906470, 2022). "Chronic myeloid leukemia (CML) was identified as a neoplastic disease of hematopoietic stem cells, arising from a fusion event termed BCR-ABL." (PMID 36058922, 2022). "In the BCR/ABL1 positive MPN classification, chronic myeloid leukemia (CML) is responsible for 15–20% of leukemias worldwide, with an incidence of 1–2/100,000." (PMID 35204792, 2022). "Then we constructed two shRNA expression plasmids targeting the BCR-ABL fusion gene, a vital marker molecule of chronic myelogenous leukemia (CML), encoding a continuously activated tyrosine kinase activity that leads to overproliferation." (PMID 35782508, 2022). "In case of chronic myeloid leukemia (CML), the BCR-ABL gene fusion is the major disease driver, and treatment involves use of tyrosine kinase inhibitor (TKI), causing remission in the vast majority of the cases." (PMID 34571968, 2021). "The promise of targeted therapies in cancer was first realized with the discovery of the fusion between BCR (breakpoint cluster region gene) and ABL1 (Abelson tyrosine-protein kinase 1) genes in chronic myelogenous leukemia (CML) patients." (PMID 34461089, 2021). "Imatinib, a first-generation tyrosine kinase inhibitor (TKI), which targets the BCR-ABL fusion protein, has brought revolutionary change to therapy for chronic myelogenous leukemia." (PMID 34938856, 2021). "MiR-150 has been reported to be overexpressed in CLL and underexpressed in chronic myelogenous leukaemia (CML), where its decreased levels are suggested to potentiate MYB and BCR-ABL expression." (PMID 34968247, 2021). "Multi-peptide vaccination with fusion peptide spanning the BCR–ABL fusion showed a specific immune response and improved disease control in patients with chronic myeloid leukemia." (PMID 34830991, 2021). "The BCR-ABL fusion gene, which is created through chromosomes 9 and 22 translocation (also called Philadelphia chromosome), is a key oncogene in chronic myeloid leukemia (CML)." (PMID 34419139, 2021). "It is approved for the treatment of chronic myeloid leukemia (CML) and its main target is chimeric kinase BCR-ABL." (PMID 33513872, 2021). "Imatinib (brand name Gleevec) is a kinase inhibitor acting against Abelson tyrosine kinase BCR–ABL, the KIT and PDGF receptors and is used for therapy of chronic myeloid leukemia (CML), gastrointestinal stromal tumors (GIST) and several other malignancies." (PMID 34409045, 2021). "In chronic myeloid leukemia (CML), fusion of the breakpoint cluster region (BCR) on chromosome 22 with the Abelson murine leukemia viral oncogene homolog 1 (ABL) tyrosine kinase of chromosome 9, results in the fusion gene BCR-ABL1." (PMID 32708107, 2020). "The BCR‐ABL fusion gene is a characteristic cytogenetic change in chronic myeloid leukemia and certain ALL patients, resulting from the fusion of the BCR gene of the long arm of chromosome 22 with the ABL gene of the long arm of chromosome 9." (PMID 32119768, 2020). "Fusion between BCR (chromosome 22q11.2) and ABL1 (chromosome 9q34) leads to chronic myeloid leukemia (CML)." (PMID 32799866, 2020). "In chronic myeloid leukemia (CML), the oncogenic fusion kinase BCR-ABL activates MAPK pathways that are suggested to promote leukemogenesis." (PMID 33255177, 2020).